KLRG1 (killer cell lectin like receptor G1)
Diseases named in the same sentence as KLRG1 in open-access papers (continued):
Sharing a sentence is not in itself a finding about the gene and the disease.
influenza (13 papers, 2011 to 2025). An acute viral infection of the respiratory tract, occurring in isolated cases, in epidemics, or in pandemics; it is caused by serologically different strains of viruses (influenzaviruses) designated A, B, and C, has a 3-day incubation period, and usually lasts for 3 to 10 days. "By using A2/M1 tetramers to identify influenza specific T cells directly ex vivo we also observed that a higher proportion of influenza-specific CD8 T cells from older donors were double positive for KLRG1 and CD57, inhibitory receptors implicated in proliferative senescence." (PMID 21887299, 2011). "We also included TIGIT+KLRG1+ CD8+ T memory cells sorted from both acute (influenza (FLU) and chronic (CMV) viral-specific T cells identified using pentamer staining." (PMID 38650930, 2024). "Klrg1+aaMAIT cells expressed a cytotoxic effector programme and protected from lethal influenza challenge." (PMID 37231163, 2023). "Testing the expression of KLRG1 in influenza-specific cells revealed a reduced proportion of KLRG1+ cells in both NP366–374 and PA224–233-specific cells of IL-7Rα449F mice." (PMID 34997007, 2022). "We found that following infection with influenza, IL-7Rα449F influenza-specific CD8 T cells have reduced expression of KLRG1 and terminal differentiation to SLEC." (PMID 34997007, 2022). "KLRG1+ Treg cells are considered a highly suppressive and terminally differentiated population of Treg cells that arise during tissue repair, such as influenza-induced lung injury, and help in tissue regeneration." (PMID 31940491, 2020). "For HLA-A2+ donors, MHC tetramer staining showed that a higher proportion of influenza-specific memory CD8 T cells from the 65+ group co-express the markers killer cell lectin-like receptor G1 (KLRG1) and CD57 compared to their younger counterparts." (PMID 21887299, 2011). "To determine whether NK cells affect the memory potential of Ag-specific CD8+ T cells, we tracked the kinetics of CD127 and KLRG1 expression on influenza-specific CD8+ T cells in the lung and MdLN 10 and 45 dpi." (PMID 33903648, 2021). "In addition to the PI3K pathway, the novel link to general viral regulator gene (CDK13) and a specific influenza T cell gene using transcriptomics (KLRG1) demonstrate the utility of our proposed framework." (PMID 25685197, 2015). "However, upon further examination of older donors, we observed that many of the tetramer+ CD8 T cells were KLRG1+CD57+, and that an increased frequency of these KLRG1+CD57+ influenza-specific cells correlated with a poor vaccination outcome for H1N1." (PMID 21887299, 2011). "Thus the KLRG1+CD57+ influenza- specific T cells, while resembling senescent cells specific for the persistent pathogen CMV, are distinct from the exhausted T cells observed in chronic HIV or HCV infection." (PMID 21887299, 2011). "We also observed upregulation of KLRG1 by the OVA-specific CD8+ T cells in all tissues tested, and to a greater degree than influenza-specific donor OT-I CD8+ T cells." (PMID 31998326, 2019). "Since KLRG1 signaling can inhibit the proliferation and function of immune cells, a reduction in KLRG1+ MAIT cells in severe influenza may reflect a dysregulation of immune cell proliferation." (PMID 40766325, 2025). "On the other hand, CD8 T cells from healthy adults that are specific for an acutely infecting pathogen, influenza, do not express significant levels of KLRG1." (PMID 21887299, 2011). "No such correlation was found when the KLRG1+CD57+ population from the total CD8 T cell population was compared with peak antibody titers post-vaccination, arguing that it is the influenza-specific T cell memory phenotype that is predictive of vaccine outcome." (PMID 21887299, 2011). "We found that influenza-specific IFNγ production by CD4 and perhaps CD8 T cells or the absence of the KLRG1+CD57+ influenza-specific tetramer positive population each independently predict influenza antibody responses upon vaccination." (PMID 21887299, 2011).
autoimmune disease (9 papers, 2016 to 2024). A disorder resulting from loss of function or tissue destruction of an organ or multiple organs, arising from humoral or cellular immune responses of the individual to their own tissue constituents. "In this review, we explore alterations in the distribution, structure, and signaling pathways of KLRG1 in immune cells and summarize its expression patterns and roles in the development and progression of autoimmune diseases, infectious diseases, and cancers." (PMID 38898461, 2024). "Given the association of TEX with better response to therapy in autoimmune disease, we explored the relationship between TIGIT+KLRG1+ TEX frequency and HLA risk alleles in the setting of immune interventions leveraging recent clinical trials." (PMID 38650930, 2024). "Abcuro, Inc. has designed a cell depleting monoclonal antibody, specific for KLRG1 as a potential treatment strategy for certain autoimmune diseases in which KLRG1+ CD8+ cells have been identified as mediators of pathology." (PMID 39281869, 2024). "Altogether, these reports highlight the therapeutic potential of KLRG1+ Tregs to prevent a variety of autoimmune diseases and GVHD." (PMID 35572605, 2022). "Targeting KLRG1+ lymphocytes may be a promising strategy for developing therapeutic agents for treating autoimmune diseases." (PMID 38898461, 2024). "In conclusion, these studies suggest that KLRG1 is mostly positively correlated with disease severity in autoimmune diseases, can serve as a marker of disease progression in patients with IBM and SLE, and has potential as a therapeutic target in patients with IBM." (PMID 38898461, 2024). "Importantly, an anti-KLRG1 mAb (ABC008) for treating autoimmune diseases and hematologic malignancies is already in development and is a novel, promising strategy for disease treatment." (PMID 38898461, 2024). "This work discovered genetic variations in KLRG1, CRTAM, SLAMF7, PTPN2, and KLRD1, which could be linked to altered PD-1-mediated cellular immune responses and may lead to autoimmune disorders." (PMID 38254179, 2024). "Recent advances have shown the crucial role of KLRG1 in the pathogenesis and progression of autoimmune disorders, infectious diseases, and malignancies, underscoring its potential utility as a promising immune cell marker for disease prediction, diagnosis, and prognostication." (PMID 38898461, 2024). "KLRG1 also plays a role in the progression of autoimmune diseases." (PMID 38898461, 2024). "As an immune checkpoint receptor, KLRG1 may play a role in autoimmune diseases by regulating the effector functions and proliferative capacities of T- and NK cells and controlling immune tolerance." (PMID 38898461, 2024). "KLRG1+ Treg cells also feature prominently in numerous autoimmune diseases." (PMID 35572605, 2022). "Thus, KLRG1+ Tregs represent a Treg population with plasticity that contributes to the pathogenesis of infections, cancer, and autoimmune diseases." (PMID 35634302, 2022). "We found elevated KLRG1 expression on T cells from patients with cancer and autoimmune disease." (PMID 27557510, 2016). "Together, these data suggest that the TIGIT+KLRG1+ CD8+ T cell population is primarily composed of TEX and is present in the peripheral blood in healthy individuals, individuals with autoimmune disease, and cancer." (PMID 38650930, 2024). "Interestingly, low KLRG1, PTPN2, and SLAMF7 levels have been observed in many autoimmune diseases, usually in the context of tissue-resident T cells." (PMID 38254179, 2024).
COVID-19 (9 papers, 2022 to 2025). A disease caused by infection with severe acute respiratory syndrome coronavirus 2. "This study identified CCR5, CYSLTR1, and KLRG1 as efficient diagnostic biomarkers for severe COVID-19 using machine learning and revealed immune regulatory features across COVID-19 progression and recovery." (PMID 40444276, 2025). "In summary, CCR5, CYSLTR1, and KLRG1 not only demonstrate significant diagnostic value for identifying severe COVID-19 patients but also play critical roles in modulating immune cell activation, differentiation, and function." (PMID 40444276, 2025). "The primary objective was to assess the association of peripheral senescent T-cells (CD28-CD57+KLRG1+) with COVID-19 vaccine-induced immunity." (PMID 37334387, 2023). "Immune infiltration analysis revealed a significant positive correlation between KLRG1 and both resting and activated NK cells, indicating its role as a molecular marker of NK cell functional status in severe COVID-19 patients." (PMID 40444276, 2025). "Severe COVID-19 patients that develop lung injury showed expanded KLRG1+ Tregs that express Cxcr3, Il10, Il12b1, Ilrb1, Tbx21, Gata3 gene signatures similar to what was found in this study." (PMID 35634302, 2022). "Metacluster #1 was more frequent in healthy donors than in COVID-19 patients and was characterized by CD4+ T cells expressing early differentiation markers (CD62L+CD95+CD127+CD28+) and low levels of KLRG1 and CD56." (PMID 39136010, 2024). "Expression analysis revealed significant differential expression of CCR5, CYSLTR1, and KLRG1 between COVID-19 ICU and non-ICU groups." (PMID 40444276, 2025). "In terms of abundance, CD38+KLRG1−CD8+ T cells (both ‘antigen’ and ‘antigen_prolif’ clusters), but not the CD38+KLRG1+CD8+ T cell clusters, were associated with the severity and trajectory of COVID-19." (PMID 37735591, 2023). "The percentage of CD57, KLRG1, CD56, NKG2A expressed by CD8+ T cells and late differentiated CD27-CD28-, EMRA CD8 subsets were not significantly different between the COVID-19+ and control cohort." (PMID 38715114, 2024).
parasitic infection (7 papers, 2010 to 2025). "During parasitic infection with Toxoplasma gondii, KLRG1+ cells represent between 40-60% of the responding tetramer-specific CD8 T cells in lymphoid and peripheral tissues." (PMID 40163479, 2025). "The amount of available data regarding the expression level and role of KLRG1 in infectious diseases, including viral, bacterial, and parasitic infections, is increasing." (PMID 38898461, 2024). "Antibody blockade of PD-1 during N. brasiliensis infection increases the number of KLRG1+ ILC-2s, which enhances the protective function of ILC-2s in parasitic infections and reduces the disease burden." (PMID 38898461, 2024). "KLRG1 can bind to ligands on the surface of ILC-2s, inhibit ILC-2 proliferation and activation, and reduce the ability of ILC-2s to produce cytokines, thereby decreasing the immune responses of ILC-2s to parasitic infection." (PMID 38898461, 2024). "While the expression levels of KLRG1 and PD-1 in T cells are normally increased during viral, bacterial or parasite infections, we found that the levels of KLRG1 and PD-1 in T cells remain the same regardless of MLKL status in MMTV-PyMT model (Extended Data." (PMID 36703228, 2023). "However, although P. chabaudi infection in mice has a prolonged acute parasitemia and a long chronic phase, few PD-1+ effector Tg CD4+ T cells (all CD62Llo, maximum of 5.7% at day 21) were transiently present, and no KLRG-1+ cells were observed (data not shown)." (PMID 21124875, 2010).
tuberculosis (7 papers, 2013 to 2024). A chronic, recurrent infection caused by the bacterium Mycobacterium tuberculosis. "On the other hand, some studies have proposed that immunosenescence plays an important role in age-associated reactivation of tuberculosis and that KLRG1 is involved in this phenomenon, as evidenced using KLRG1 knock-out mice." (PMID 37753486, 2023). "It was found that KLRG1 expression on T cells increases during M. tuberculosis infection during aging and decreases after treatment of TB, suggesting an association with KLRG1 expression and disease progression." (PMID 38903242, 2024). "Comparing wild-type mice with KLRG1−/− mice, the latter had a significantly longer survival, beyond 600 days, and maintained lower levels of M. tuberculosis throughout chronic infection from day 60 onward." (PMID 38903242, 2024). "Thus, TB is associated with diminished CD4+ T cell response through KLRG1, with KLRG1 being a marker involved in the immunosenescence of M. tuberculosis." (PMID 38903242, 2024). "The long-term protection induced against tuberculosis can be associated with other memory T cells such as the TRM cells; KLRG-1/PD-1 marked T cells are one of the most prominent subsets." (PMID 37520577, 2023). "For instance, short lived, highly apoptotic, terminally differentiated and effector cytokine secreting KLRG1+CD4+ T cell populations are significantly upregulated in tuberculosis patients." (PMID 35572605, 2022). "In contrast, two papers reported the presence of a subset of Foxp3+ cells within KLRG1+CD4+ cells isolated from tuberculosis patient PBMC and ovarian cancer tumor microenvironment." (PMID 35572605, 2022). "In support of these findings, it has been demonstrated that mucosal BCG vaccination, as well as the CAF01-adjuvanted fusion protein Ag85B-ESAT6, induces an antigen specific KLRG1- CD4+ T cell population, which confers better protection against tuberculosis." (PMID 35572605, 2022). "In vivo analyses with murine models showed that the senescence marker known as killer cell lectin-like receptor G1 (KLRG1), is expressed at higher levels in T cells upon M. tuberculosis infection during aging and decreases after pharmacologically treating tuberculosis." (PMID 37753486, 2023). "It has been reported that HIV+ patients who develop tuberculosis-associated immune reconstitution inflammatory syndrome (TB-IRIS) as a result of long-term activation present a higher number of exhausted cells (PD-1+, KLRG-1+) that are not effective in combating the TB infection." (PMID 33977111, 2021).
chronic hepatitis B (6 papers, 2021 to 2024). "In a recent study, CD8+ T cells from long-term antiviral-treated chronic hepatitis B (CHB) patients demonstrated higher KLRG1 expression than CD8+ T cells from healthy controls (HCs)." (PMID 38776335, 2024). "Wijaya reported that in chronic hepatitis B infection, KLRG1+ NK cells exert antifibrotic effects by releasing highly cytotoxic proteins and IFN-γ." (PMID 36930687, 2023). "The frequency of killer cell lectin-like receptor subfamily G member 1 (KLRG1)-expressing NK cells displayed anti-fibrotic effects in patients with chronic hepatitis B (CHB)." (PMID 37239062, 2023). "CD8+ T cells from 190 patients with chronic hepatitis B were analyzed ex vivo for checkpoint and apoptosis markers, transcription factors, cytokines and subtypes in 190 patients with chronic hepatitis B. KLRG1+ and KLRG1− CD8+ T cells were sorted for transcriptome analysis." (PMID 38776335, 2024). "A high dose of Ad-HBV-Luc developed into chronic hepatitis B accompanied by dysfunctional CD8 T cells characterized by high expression of PD1 and TOX and low expression of KLRG1 and GzmB." (PMID 34835079, 2021).
helminth infection (6 papers, 2020 to 2023). "In one study, the authors found that PD-1 negatively regulated the function of KLRG1+ ILC2s derived from the murine model of worm infection and PBMCs of human HDs in vitro." (PMID 34194433, 2021). "These KLRG1+CD90lo ILC2 may be similar to the inflammatory ILC2 that have been reported to proliferate in the small intestine, then migrate to the lung and other tissues in response to helminth infection or IL-25 treatment." (PMID 35534698, 2022). "However, IL-25 treatment reportedly promotes migration of inflammatory ILC2s, generally defined as IL-33 receptor low/IL-25 receptor high/killer cell lectin-like receptor G1 (KLRG1)high ILC2s, from the small intestine to the lung or mesenteric lymph nodes during helminth infection." (PMID 33403383, 2021).
Sepsis (6 papers, 2017 to 2025). Sepsis is defined as life-threatening organ dysfunction caused by a dysregulated host response to infection. "It showed association with CD2, IL2RB, and IL7R in adult SIRS and KLRG1 and TGFBR3 in adult sepsis, among others." (PMID 32318053, 2020). "In this study, ROC analysis results further indicate that the four hub genes (MYBL1, KLRG1, STOM and MS4A4A) had good diagnostic performance in sepsis, close to that of genes previously reported." (PMID 29237456, 2017). "Among those novel hub genes, we assessed the expression patterns of MYBL1, KLRG1, STOM and MS4A4A from the top 2 sepsis-associated modules (module “midnight blue” and module “cyan”) by qPCR." (PMID 29237456, 2017). "The expression levels of MYBL1 and KLRG1 in the sepsis group were significantly lower than those of the control group (P < 0.001 respectively)." (PMID 29237456, 2017). "Although we observed increased NK frequencies in CCI, we have previously demonstrated via scRNA-seq analysis that cytotoxic genes (KLRC3, KLRC1, and KLRG1) of NK cells were downregulated in patients with late sepsis (CCI and rapid recovery) (n=4), suggesting dysregulation of these cells." (PMID 39691721, 2024). "Both the qPCR results and ROC analysis results suggest that the four hub genes (MYBL1, KLRG1, STOM and MS4A4A) could be novel diagnostic biomarkers for pediatric sepsis." (PMID 29237456, 2017). "qPCR results suggest hub genes (MYBL1, KLRG1, STOM and MS4A4A) in the candidate modules as promising potential transcriptomic markers for pediatric sepsis diagnosis." (PMID 29237456, 2017). "S1PR5, GNLY, CD247, KLRG1, IL-1R2, AUTS2, IL-2Rβ, ARG1, TGFBR3, TLR5 and PRF1 in the top 80 genes in the two modules were located toward the center of the co-expression network, and CD247, IL-2Rβ, TGF-βR3 and IL-1R2 were identified as core genes in sepsis." (PMID 36855106, 2023). "Although the number of Treg was not altered after sepsis, a higher number of Treg expressing inhibitory markers was noticed, specifically a higher number of KLRG1+ Treg in CLP compared to SHM animals, and a higher number of PD-1+ and CTLA-4+, but not of KLRG1+ Treg in CLP+STZ compared to SHM+STZ." (PMID 41142792, 2025).
Autoimmunity (5 papers, 2022 to 2024). The occurrence of an immune reaction against the organism's own cells or tissues. "Here we review the current literature on KLRG1 with an emphasis on the KLRG1+ Treg subset role during cancer development and autoimmunity." (PMID 35572605, 2022). "KLRG1 deficient animals develop without any evidence of abnormality in major organs or signs of autoimmunity/inflammatory disorders." (PMID 35572605, 2022). "As discussed in this review, targeting KLRG1+ Treg cells to control tumor development, to prevent autoimmunity, or to control infectious diseases might benefit the host." (PMID 35572605, 2022). "Although Ly6C+ naive and PD1+ effector populations were demonstrated to be affected in an intrinsic manner, KLRG1+ SLEC-like effectors were not, and this population was rescued in mixed chimeric WT:Pepd−/− mice alongside loss of hallmarks of autoimmunity." (PMID 36637239, 2023). "CD57 and KLRG1 are commonly used as senescence markers in CD4+ and CD8+ T cells to assess T cells fitness after Ebola vaccination, in cancer or autoimmunity, but their relevance in Tregs is not well defined." (PMID 35931871, 2023).